SLC27A2 (solute carrier family 27 member 2)
Description:
Mediates the import of long-chain fatty acids (LCFA) into the cell by facilitating their transport across cell membranes, playing an important role in hepatic fatty acid uptake. Also functions as an acyl-CoA ligase catalyzing the ATP-dependent formation of fatty acyl-CoA using LCFA and very-long-chain fatty acids (VLCFA) as substrates, which prevents fatty acid efflux from cells and might drive more fatty acid uptake. Plays a pivotal role in regulating available LCFA substrates from exogenous sources in tissues undergoing high levels of beta-oxidation or triglyceride synthesis. Can also activate branched-chain fatty acids such as phytanic acid and pristanic acid. May contribute to the synthesis of sphingosine-1-phosphate. Does not activate C24 bile acids, cholate and chenodeoxycholate. In vitro, activates 3-alpha,7-alpha,12-alpha-trihydroxy-5-beta-cholestanate (THCA), the C27 precursor of cholic acid deriving from the de novo synthesis from cholesterol. However, it is not critical for THCA activation and bile synthesis in vivo. [Isoform 1]: Exhibits both long-chain fatty acids (LCFA) transport activity and acyl CoA synthetase towards very long-chain fatty acids. Shows a preference for generating CoA derivatives of n-3 fatty acids, which are preferentially trafficked into phosphatidylinositol. [Isoform 2]: Exhibits long-chain fatty acids (LCFA) transport activity but lacks acyl CoA synthetase towards very long-chain fatty acids.
Synonyms: VLACS; VLCS; ACSVL1; FACVL1; FATP2; hFACVL1; HsT17226
Tractability: Antibody: UniProt places it where antibodies can reach, with high confidence; its Gene Ontology location is reachable by antibodies, with high confidence; UniProt predicts a signal peptide or a membrane-spanning region. PROTAC: ubiquitination databases record sites on it; its protein half-life has been measured; a small molecule that binds it is known.
Target class: Electrochemical transporter; Transporter; SLC27 family of fatty acid transporters; SLC superfamily of solute carriers
Gene: Protein-coding gene on chromosome 15 (50,182,196 to 50,236,445, forward strand). Ensembl gene ENSG00000140284.
Subcellular location: Endoplasmic reticulum membrane; Peroxisome membrane; Cell membrane; Microsome
Pathways (Reactome):
Metabolism: Alpha-oxidation of phytanate; Beta-oxidation of very long chain fatty acids; Fatty acyl-CoA biosynthesis; Synthesis of bile acids and bile salts via 24-hydroxycholesterol; Synthesis of bile acids and bile salts via 7alpha-hydroxycholesterol
Immune System: Neutrophil degranulation
Protein localization: Peroxisomal protein import
Gene Ontology:
Molecular function: enzyme binding; long-chain fatty acid transmembrane transporter activity; long-chain fatty acid-CoA ligase activity; phytanate-CoA ligase activity; pristanate-CoA ligase activity; very long-chain fatty acid-CoA ligase activity; arachidonate-CoA ligase activity; cholate-CoA ligase activity; fatty acid transmembrane transporter activity
Biological process: bile acid biosynthetic process; fatty acid alpha-oxidation; fatty acid beta-oxidation; long-chain fatty acid import into cell; long-chain fatty acid metabolic process; methyl-branched fatty acid metabolic process; bile acid metabolic process; fatty acid beta-oxidation using acyl-CoA oxidase; fatty-acyl-CoA biosynthetic process; fatty acid metabolic process; long-chain fatty acid transport
Cellular component: endoplasmic reticulum lumen; endoplasmic reticulum membrane; extracellular exosome; peroxisomal membrane; cytosol; plasma membrane; specific granule membrane; endoplasmic reticulum; peroxisome
Genetic constraint (gnomAD): Loss-of-function variants: 41 observed, 48.21 expected, observed/expected ratio (o/e) 0.85, 90% interval 0.66 to 1.1. The upper end of that interval is the gene's LOEUF score, 1.1, which puts it in group 4 of 6, group 1 being the genes least tolerant of losing a copy. Missense variants: 639 observed, 698.16 expected, observed/expected ratio (o/e) 0.92, 90% interval 0.86 to 0.98. Synonymous variants: 251 observed, 261.96 expected, observed/expected ratio (o/e) 0.96, 90% interval 0.86 to 1.06.
Homologues: Orthologues: chimpanzee SLC27A2 (99% identical), macaque SLC27A2 (89% identical), rabbit SLC27A2 (86% identical), pig SLC27A2 (86% identical), dog SLC27A2 (85% identical), mouse Slc27a2 (82% identical), rat Slc27a2 (82% identical), guinea pig SLC27A2 (82% identical), tropical clawed frog slc27a2 (58% identical), Drosophila melanogaster Fatp2 (37% identical), Drosophila melanogaster Fatp3 (35% identical), Drosophila melanogaster Fatp1 (35% identical), and 23 more. Paralogues in human: SLC27A6 (51% identical), SLC27A5 (46% identical), SLC27A3 (43% identical), SLC27A4 (40% identical), SLC27A1 (40% identical), ACSL6 (21% identical), ACSL1 (21% identical), ACSL5 (20% identical), ACSL3 (19% identical), ACSL4 (17% identical), ACSBG1 (17% identical), ACSBG2 (16% identical).
Diseases named in the same sentence as SLC27A2 in open-access papers:
SLC27A2 is named in the same sentence as 71 diseases in open-access papers, as found by Europe PMC text mining. Sharing a sentence is not in itself a finding about the gene and the disease. The quoted sentences say what the papers report.
Hepatic steatosis (21 papers, 2012 to 2025). Steatosis is a term used to denote lipid accumulation within hepatocytes. "Cd36 and Slc27a2 are both involved in lipid synthesis and oxidation, and fatty acid metabolism, oxidation; and only Cd36 is involved in fatty acid transport and hepatic steatosis." (PMID 38787127, 2024). "In this work, we report the importance of SLC27A2/FATP2, a fatty acid transporter, in initiating starvation-induced hepatic steatosis." (PMID 38467419, 2024).
Obesity (16 papers, 2012 to 2025). Accumulation of substantial excess body fat. "Interestingly, SLC27A2′s expression has been linked to obesity development in rat models, suggesting a role in lipid accumulation and weight gain." (PMID 40647532, 2025). "scWAT gene expression of SLC27A2, CNR1, DAGLA, MGLL, FAAH, SLC27A1 and SLC27A2 were lower in individuals living with healthy obesity." (PMID 38024342, 2023). "FATP2, also known as Slc27a2, was found to modulate the obesity index and cardiorespiratory fitness in this group." (PMID 36830344, 2023). "Genes related to the inflammation including Slc27a2, Gpnmb, Gstm6 and Acsl6, can be classified into category B. Obesity can be considered as a chronic inflammation with low grade, and Slc27a2 was reported to be a potential marker of obesity." (PMID 35864275, 2022). "We previously reported 92% lower expression of SLC27A2 in scWAT of individuals living with obesity at study entry." (PMID 35247847, 2022). "We, for the first time, identify differences in the expression of genes involved in fatty acid handling in individuals living with obesity, including SLC27A2, which is required for the metabolism of DHA to further bioactive signalling molecules." (PMID 35247847, 2022). "The children who were breastfed showed higher expressions of SLC27A2, FASN, PPARα, and INSR, and were at lower risk to develop obesity." (PMID 34073649, 2021). "The downregulation of SLC27A2 expression is negatively correlated with diabetes and obesity-related traits, including insulin resistance and BMI." (PMID 32337289, 2020). "According to these data, higher expressions of SLC27A2, FASN, PPARα, and INSR genes in the children’s blood reflected a protective role of breastfeeding, as these genes are indicators of a lower risk of developing insulin resistance and dyslipidemia linked with obesity in children." (PMID 34073649, 2021). "In another integrative methylome–transcriptome analysis, seven key genes were identified—CCRL2, GPT, LGALS12, PC, SLC27A2, SLC4A4, and TTC36—that were hypermethylated in obesity and concurrently showed reduced expression." (PMID 41303351, 2025). "Accordingly, PLA2G2A and PLA2G4A genes were up-regulated by omega-3 polyunsaturated fatty acids supplementation, whereas SLC27A2, CNR1, DAGLA, MGLL, FAAH, SLC27A1, and SLC27A2 genes were found to be down-regulated in people living with healthy obesity." (PMID 38024342, 2023). "In summary, we successfully identified seven key genes, namely, CCRL2, GPT, LGALS12, PC, SLC27A2, SLC4A4, and TTC36, which are involved in obesity occurrence and development likely through the immune microenvironment." (PMID 36313453, 2022). "In this study, not only SLC4A4 but also SLC27A2 were both significantly downregulated in obese patients, which to a certain extent supports previous studies and suggests that these two genes might be key genes requiring more attention in the future exploration of the obesity mechanism." (PMID 36313453, 2022). "In this study, by analyzing three GEO datasets and verifying in 24 patients, we identified that CCRL2, GPT, LGALS12, PC, SLC27A2, SLC4A4, and TTC36 might be the key genes that play an important role in obesity pathogenesis." (PMID 36313453, 2022). "We reported that subsequent lower activation of DHA by SLC27A2, may result in less conversion of DHA to the DHA containing ethanolamide, providing a mechanism for the impaired synthesis of DHA-ethanolamide following LC n-3 PUFA intervention in obesity." (PMID 35247847, 2022). "We report lower expression of SLC27A2 which may contribute to reduced acyl-Co-A ester formation, and subsequently impaired generation of 14-HDHA in response to LC n-3 PUFA intervention in individuals living with obesity." (PMID 35247847, 2022).
Obesity (continued). "In the current analysis, this lower expression of SLC27A2 may contribute to lower proportions of Rvs and HDHAs observed at study entry and may explain the lack of formation of 14-HDHA in response to LC n-3 PUFA intervention in individuals living with obesity." (PMID 35247847, 2022). "We further highlight the role of adipose tissue and the potential impact of obesity in viral responses and that OAS genes and SLC27A2 may be novel targets for future therapeutic intervention." (PMID 35247847, 2022).
melanoma (14 papers, 2020 to 2025). A malignant, usually aggressive tumor composed of atypical, neoplastic melanocytes. "LPL, CD36, FATP1 (SLC27A1), and FATP2 (SLC27A2), implicated in increased FA uptake into melanoma cells, are unaffected by point mutation in cancer and display gene amplification in 2%–8% of cases." (PMID 35732120, 2022). "For example, blocking FATP2 in melanoma cells in the aging microenvironment can inhibit their lipid accumulation, and SLC27A2 specific inhibitors can slow down tumor growth, making SLC27A2 a beneficial target for targeted treatment of melanoma cells." (PMID 38664735, 2024). "FATP1 (SLC27A1) accelerates melanoma initiation, and FATP2 (SLC27A2) confers melanoma resistance to BRAF and MEK inhibition by promoting FA uptake from the microenvironment." (PMID 35764645, 2022). "Upregulation of additional genes from the bile acid and peroxisome signaling pathways was also evident in TIL gene and pathway expression analysis, including upregulation of SOD1, ACSL5, FADS2, CAT, DHCR24, SLC27A2, and IDH2 in melanoma TILs compared to pCD8s." (PMID 38023136, 2023). "Furthermore, in vitro and in vivo analyses using glioblastoma, melanoma, and HNSQ cell lines supported the anti-tumor effects of SLC27A2, suggesting that FATP2 can induce ferroptosis in several cancers, including EBV-infected lymphoma." (PMID 38719806, 2024). "SLC27A2 could regulate cells peroxisomes and mitochondria FAO in melanoma cells to induce drug resistance." (PMID 37041476, 2023). "Marked morphological changes were observed in glioblastoma (A-172) and melanoma (COLO679) cells, but not in HNSQ (HSC-2) cells following ectopic SLC27A2 expression." (PMID 38719806, 2024).
thyroid cancer (11 papers, 2021 to 2025). "This aligns with findings in differentiated thyroid cancer, where SLC27A2 influenced the C-FOS proto-oncogene expression." (PMID 40647532, 2025). "According to studies, SLC27A2 alters the proto-oncogene c-Fos in differentiated thyroid cancer, which affects cell growth and differentiation." (PMID 36613632, 2022). "In this study, the expression of SLC27A2 was analyzed in cancer and paracancerous tissue samples from 98 thyroid cancer patients, and we performed ROC analysis to confirm the diagnostic value." (PMID 34854499, 2022). "The expression level of SLC27A2 was upregulated in differentiated thyroid carcinoma tissues compared with normal adjacent tissues, and the overexpression of SLC27A2 promoted the proliferation and migration of tumors." (PMID 34854499, 2022). "Conversely, SLC27A2 can promote cancer cell proliferation and migration in thyroid cancer." (PMID 35927229, 2022). "In addition, upregulation of SLC27A2 promotes proliferation and invasion of differentiated thyroid cancer cells." (PMID 36324578, 2022).
lung carcinoma (10 papers, 2019 to 2025). "Research has shown that SLC27A2 induces cisplatin resistance in lung cancer stem cells through negative regulation of downstream signaling pathways, and the decrease in SLC27A2 is associated with chemotherapy response and poor patient survival." (PMID 38664735, 2024). "SLC27A2 has been found to be under-expressed in many tumors, such as ovarian and lung cancers, and is associated with low survival and chemotherapy resistance." (PMID 36869083, 2023). "SLC27A2, as a tumor suppressor gene, is associated with multiple human malignancies, for instance, lung cancer, ovarian cancer, and prostate cancer." (PMID 35927229, 2022). "Low expression of Asparaginase-Like 1 Protein (ASRGL1) has been suggested as a marker for poor prognosis in endometrial carcinoma, whereas reduced levels of Solute carrier family 27 member 2 (SLC27A2) have been associated with poor survival in lung cancer." (PMID 31337362, 2019). "Accumulated evidence indicates that SLC27A2 is significantly underexpressed in various human malignancies, including ovarian, prostate, and lung cancers." (PMID 35927229, 2022). "Previous studies have shown that SLC27A2 in ovarian and lung cancers alleviates their resistance to chemotherapeutics." (PMID 35927229, 2022). "SLC27A2 (solute carrier family 27 member 2; FC 1.76) was also upregulated by the four tumors and played an important role in maintaining lung cancer cells that were sensitive to cisplatin." (PMID 34623465, 2022). "Thapsigargin-induced ER stress results in the downregulation of ACSL3, ACSL4 and solute carrier family 27 member 2 (SLC27A2) in lung cancer." (PMID 31344914, 2019). "By downregulating SLC27A2, cisplatin resistance in lung cancer may be induced via the Bmi1-ABCG2 pathway, which can lead to cisplatin chemotherapy resistance in OvCa." (PMID 37256178, 2023).
breast carcinoma (8 papers, 2013 to 2025). "For TGFB2-dependent biomarkers, elevated TGFB2 mRNA expression is a prognostic biomarker associated with breast cancer patients that is correlated with improved OS outcomes at high expression levels of GDAP1, TBL1XR1, RNFT1, HACL1, SLC27A2, NLE1, and TXNDC16." (PMID 41373732, 2025). "The potential of SLC27A2 as a therapeutic target is further supported by studies in breast cancer, where inhibition of SLC27A2 was shown to suppress proliferation and induce apoptosis in tumor cells." (PMID 40647532, 2025). "Increased levels of SLC27A2 were validated at both the mRNA and protein levels in breast cancer cell lines, and the knockdown of SLC27A2 inhibited cell proliferation and cell cycle in these cells." (PMID 41373732, 2025). "In breast cancers, SLC27A2 mRNA expression constituted part of a four-gene signature that stratified patients into low and high-risk groups." (PMID 41373732, 2025). "The very long chain synthetase, SLC27A2 (also known as ACSVL1), a peroxisomal enzyme that activates long-chain fatty acids prior to oxidation, is overexpressed in receptor-positive, luminal subtypes of breast cancer." (PMID 28412757, 2017). "Here, we present a validation of the prognostic role of five selected candidate biomarkers (CCNB2, ASPM, KIAA0101, CDCA7, and SLC27A2) included in these gene signatures using an independent breast cancer cohort." (PMID 23282137, 2013). "The purpose of the present study was to investigate the prognostic value of the candidate biomarkers CCNB2, ASPM, CDCA7, KIAA0101, and SLC27A2 in breast cancer." (PMID 23282137, 2013). "Recent research in breast cancer has even revealed a role for SLC27A2 in nucleotide metabolism." (PMID 40647532, 2025). "In cases dependent on TGFB2, increased mRNA expression of TGFB2 alongside higher levels of GDAP1, TBL1XR1, RNFT1, HACL1, SLC27A2, NLE1, or TXNDC16 was correlated with improved OS among breast cancer patients, of which four genes were upregulated in tumor tissues (SLC27A2, TXNDC16, TBL1XR1, GDAP1)." (PMID 41373732, 2025). "In order to characterize whether these genes are regulated by methylation levels, we downloaded illumina methylation 450 K beadChip data of 890 breast cancer samples from TCGA project, and 4 genes (PXDNL, SLC27A2, KLRB1 and IGHV1-12) were detected." (PMID 36869083, 2023).
steatosis (7 papers, 2018 to 2025). Increased lipid within the cytoplasm of cells. "To test the evolutionary conservation of SLC27A2/FATP2 in starvation-induced steatosis, we turned to Drosophila, which shows the robust accumulation of lipid droplets in oenocytes, the evolutionary homologues of hepatocytes in the fly." (PMID 38467419, 2024).
Insulin resistance (6 papers, 2019 to 2023). Increased resistance towards insulin, that is, diminished effectiveness of insulin in reducing blood glucose levels. "Serpine 1, an adipokine in thrombosis and insulin resistance regulation, was substantially upregulated, and genes involved in lipid metabolism, including Slc27a2, Acsm3, Acot1, and Ucp3, were dramatically decreased in BAT of BMRKO-HFD mice." (PMID 37734559, 2023). "In addition, for circFAT3 KD, genes related to insulin signaling and insulin resistance (PPARGC1A, SLC27A2, PPARGC1B, PRKCQ, GYS1, and IRS1) were the top hits." (PMID 36840844, 2023). "SLC27A2 may be a key gene in the PPAR signaling pathway, the adipocytokine signaling pathway, and the insulin resistance pathway." (PMID 32337289, 2020).
diabetes (5 papers, 2019 to 2025). "Considerable evidence has revealed that SLC27A2 is related to various metabolic disorders or diseases, such as lipotoxicity, oxidative stress and energy production, nonalcoholic fatty liver disease (NAFLD), type 2 diabetes mellitus (T2DM), kidney fibrosis, and cancers." (PMID 37041476, 2023).
diabetic kidney disease (4 papers, 2022 to 2025). Progressive kidney disorder caused by vascular damage to the glomerular capillaries, in patients with diabetes mellitus. "Even though improvement of diabetic kidney disease could be due to the absence of proximal tubule FATP2-dependent fatty acid uptake, global Slc27a2 knockout mice also exhibited remarkably reduced fasting glycemia, which could have conferred indirect kidney benefits." (PMID 39529801, 2024).
neuroblastoma (4 papers, 2022 to 2026). Neuroblastoma (NB) is the most common solid, extracranial childhood tumor. "MYCN upregulates SLC27A2 expression to enhance FAs uptake, supporting neuroblastoma survival and tumor growth." (PMID 38753091, 2024). "Genomic knockout of SLC27A or pharmacological inhibition of SLC27A2 significantly attenuates the growth of MYCN-amplified neuroblastoma cell lines and tumors." (PMID 36077650, 2022). "Further investigation identified SLC27A2, encoding FATP2, as a direct target gene of MYCN for transcriptional upregulation in neuroblastoma cells, leading to increased fatty acid uptake for glycerolipid synthesis." (PMID 36077650, 2022). "SLC27A2-mediated fatty acid uptake is crucial for the survival of MYCN-amplified neuroblastoma cells." (PMID 36077650, 2022). "Moreover, SLC27A2 inhibition synergizes with chemotherapy in limiting neuroblastoma growth in various animal models." (PMID 36077650, 2022).